EPHB2 (EPH receptor B2)
Diseases named in the same sentence as EPHB2 in open-access papers (continued):
Sharing a sentence is not in itself a finding about the gene and the disease.
tumor (continued). "Key to solving this conundrum will be to stratify poorly differentiated tumours, according to whether they cluster with Lgr5+EPHB2+ ISCs or display methylation of CSC-associated Wnt-target genes, to identify patients that may benefit from Wnt antagonists or agonists, respectively." (PMID 33673710, 2021). "Together, these data position EPHB2 as a multifunctional oncogene that simultaneously promotes proliferation, metastasis, and survival – three critical processes in tumor progression." (PMID 41322437, 2025). "A fusion protein EPN-ZFTA binds to the proximal enhancers of EphB2, which leads to aberrant expression of EphB2 and tumor progression." (PMID 40943224, 2025). "Specifically, F. nucleatum-infected GC cells were shown to secrete exosomes enriched in lncRNA HOTTIP, which promote tumor progression through the miR-885-3p/EphB2/PI3K/AKT axis." (PMID 40871411, 2025). "Silencing R-Ras blocks EphB2 activity, and its phosphorylation correlates with tumor grade and EphB2 expression, reinforcing this invasive pathway." (PMID 41200151, 2025). "The differing correlations of TOP2A and EPHB2 with immune infiltrates underscore their distinct roles in shaping the tumor microenvironment." (PMID 40958237, 2025). "Functionally, our experiments using the RL95-2 model system comprehensively characterized the tumor-promoting effects of EPHB2." (PMID 41322437, 2025). "Functionally, ephrin-B1 modulates multiple pathways, including p38, MSK1/2, Stat1/2/4/5a/6, and paxillin, following ligand stimulation or EphB2 inhibition, suggesting broad influence over tumor behavior." (PMID 41200151, 2025). "Understanding the specific pathways and mechanisms by which EPHB2 influences tumor behavior can lead to the development of targeted therapies aimed at blocking EPHB2 function." (PMID 41322437, 2025). "Given their roles in tumor progression, EphB2 has emerged as a promising target for monoclonal antibody (mAb)-based therapeutic strategies." (PMID 40943224, 2025). "By interfering with EPHB2 expression, it is possible to disrupt these processes, thereby inhibiting tumor growth and progression." (PMID 41322437, 2025). "The Eph receptor family tyrosine kinase EPHB2 has an expression profile that is often dysregulated in various types of disease, with its expression often being positively correlated with tumor metastasis." (PMID 40485734, 2025). "On the other hand, EphB2 activation was related to high levels of migration and invasion in vitro along with tumor size, metastasis, clinical staging, and poor survival." (PMID 39839790, 2024). "Mutations that impair kinase function of Eph receptors, such as EphB2, EphA3, EphA5, are frequently found in cancer, suggesting a tumor suppressor role for Eph receptor forward signaling." (PMID 38811954, 2024). "Conversely, other authors demonstrated that the average expression of EphB2 protein in CRC was more frequently expressed in the tumor center, the most hypoxic region." (PMID 38651144, 2024). "EphB receptors, particularly EphB2, are crucial for maintaining cellular homeostasis and regulating stem cell function, while EphA2 and ephrinA1 contribute to tumor progression and malignant transformation." (PMID 39839790, 2024). "EphB2 acts as a tumor suppressor by regulating cell migration and compartmentalization, and its dysregulation is influenced by genetic mutations, epigenetic modifications, and microenvironmental factors." (PMID 38651144, 2024). "The first relationship of EphB2 in GC was reported in 1994, attributing its overexpression to chromosomal locus 1p36, generally considered the tumor suppressor locus of colon cancer." (PMID 39839790, 2024). "We found that both E2F1 and EPHB2 expression is increased in tumor tissue compared to healthy lung and that high expression is associated with a trend towards worse prognosis, even if not reaching statistical significance." (PMID 37980331, 2023).
tumor (continued). "Transcriptome sequencing revealed that EPHB2 was important in the communication between tumor and endothelial cells." (PMID 37091977, 2023). "HIF-1 regulates EPHB2 and activates the TGFβ pathway induced tumor cells to prevent T-cell from infiltrating into tumor tissues." (PMID 37091977, 2023). "EPHB2 expression is upregulated by hypoxia-inducible factor (HIF-1) in tumor cells like Scissor_C1, which secretes EPHB2 exotically." (PMID 37091977, 2023). "EPHB2 is overexpressed in many tumors, including lung, and exerts mainly a tumor-promoting function." (PMID 37980331, 2023). "Immunohistochemistry results indicated that COL1A1 was highly expressed in tumor tissues, but more abundantly expressed in the stromal, whereas EPHB2 was also highly expressed in tumor tissues." (PMID 37091977, 2023). "Circ-MELK is a sponge for the tumor-suppressing miR-593, specifically targeting the oncogenic gene Eph receptor B2 (EphB2)." (PMID 35883576, 2022). "EphB2 is a significant member of the Eph receptor family, which was thought to be distributed on tumor cells and endothelial cells in previous researches." (PMID 35223830, 2022). "Although previous studies reported that EPHB2 promoted monocyte activation and T-cell migration, studies investigating the regulation of tumor immunity by EPHB2 are still unavailable." (PMID 36032135, 2022). "Overall, EphB2 serves as a tumor promoter in most cases, facilitating tumor cell proliferation, invasion, and migration through different signaling pathways." (PMID 35223830, 2022). "Targeting EphB2 with rAAV-8-shEphB2 inhibited HCC tumor development and obviously sensitized HCC cells to sorafenib in an HCC immunocompetent mouse model." (PMID 35223830, 2022). "We further characterized the Gln metabolism of TME and investigated the Gln metabolism-related gene EPHB2 to provide a theoretical framework for anti-tumor strategy targeting Gln metabolism." (PMID 36032135, 2022). "Despite EphB2′s potential tumor suppressor effect in PCa cells, little is known about the role of the cognate ligands, EFNBs, in the TME." (PMID 35565468, 2022). "Cutaneous squamous cell carcinoma (CSCC)-derived cell lines and tumor tissues were reported to express increased levels of EphB2 mRNA." (PMID 35223830, 2022). "EphB2 receptors were highly expressed in ISC, and EphB2 + ISC-like tumor cells promoted CRC recurrence after primary tumor excision in immunocompromised mice." (PMID 36348319, 2022). "Low expression of EphB2 was significantly correlated with advanced clinical stage, muscular invasion, higher tumor grade, and a high incidence of cystectomy." (PMID 35223830, 2022). "Eph receptor B2 (EphB2) has been demonstrated to play a crucial modulatory role in tumor progression." (PMID 35223830, 2022). "The blockage of EphB2 and EphB3 signaling accelerated the carcinogenesis process, indicating their tumor suppressive function." (PMID 35269901, 2022). "Perplexingly, EphB2 can function as both tumor promoters and suppressors in different cellular contexts." (PMID 35223830, 2022). "These tumours have a CpG Island Methylator Phenotype (CIMP) characterized by the hypermethylation of tumour suppressor gene promoters, like EPHB2, leading to overactivation of MAPK pathway, and a high level of MSI." (PMID 34359657, 2021). "In conclusion, the present correlative data, in conjunction with our previous in vitro and in vivo data, led to a model whereby in a normal context, EphB2-mediated autophagy triggers pro-apoptotic signals, resulting in tumor growth inhibition." (PMID 34360867, 2021). "The expression of EPHB2, IL-13, MAP2, RPN2, and TRAF5 was correlated with microsatellite instability (MSI), while the expression of IL-13, RPN2, and TRAF5 was related to tumor mutation burden (TMB)." (PMID 33937013, 2021). "The tumour-suppressor function of EphB2 and EphB3 is thought to be reliant on their ability to compartmentalise tumour cells, which involves E-cadherin-mediated adhesion." (PMID 33430066, 2021).
tumor (continued). "Taken together, these data show the clinical validity of a model whereby EphB2, along with its cognate ephrin ligands, have dual anti- and pro-tumor progression effects." (PMID 34360867, 2021). "Higher levels of EphB2 expression are observed in GC tumour tissue than in adjacent normal or benign gastric tissue specimens, which include the transcript level and protein expression." (PMID 32226496, 2020). "The staining scores of EphB2 were significantly higher in malignant tumour tissues than benign ones (P= 0.018)." (PMID 32226496, 2020). "Our research shows that the levels of EphB2 are significantly elevated in tumour tissue including gene and protein expression." (PMID 32226496, 2020). "The results therefore indicate that EphB2 plays a pro-tumour role in GC and present the therapeutic potential for the treatment of GC." (PMID 32226496, 2020). "This switch in the expression of EphB4 and EphB2 would provide survival advantages to tumor cells during tumor progression." (PMID 32316101, 2020). "In the tumor microenvironment, upregulation of ephrin-A2, ephrin-A3, EphB2, and EphB4, to name a few, on vascular cells in response to tumor factors has been the most well-studied." (PMID 31333644, 2019). "As seen in in vitro co-culture studies, EphA2, EphB2 and EphB4 phosphorylation was reduced in whole tumour lysates of Tie2PEKO animals, independently of changes in gene expression." (PMID 28719590, 2017). "In line with our functional assays, we observed changes in the expression of proteins that play a critical role in tumor cell growth, proliferation, invasion, and cell survival pathways in combined EphB2 downregulated and irradiated group versus other groups." (PMID 28360821, 2017). "A tumor suppressor role for EPHB2 through induction of autophagic cell death via concomitant activation of the ERK1/2 and PI3K pathways has also been described." (PMID 27058903, 2016). "We produced a highly potent eA5-based cytotoxin that kills tumor cells over-expressing receptors EphA3, EphA2, and also EphB2." (PMID 27494882, 2016). "CSC-like cells were independently isolated from CRC cells using CD133, CD44 or EphB2-high as markers and confirmed by tumor sphere formation assay." (PMID 27833077, 2016). "Our data suggest a model in which ephrinB2 loss promotes GBM invasion by increasing the intrinsic invasive capacity of tumour cells and by avoiding repulsive interactions with the EphB2/B4 expressing parenchyma, thereby reducing tumour compartmentalization." (PMID 27470974, 2016). "In this context, EphB receptors are expressed as Wnt targets, with EphB2 characterized as a tumor suppressor to constrain tumor growth in ApcMin/+ mice, whereas EphB4 promotes cancer progression." (PMID 27589803, 2016). "More importantly, they highlight a potential avenue for tumor formation involving retention of a neural stem cell state upon EphB2/ephrin-B activation that ultimately results in cellular transformation." (PMID 25801123, 2015). "EphB2-driven mouse tumor cells were implanted intracranially into recipient mice at the same coordinates used to create our model." (PMID 25801123, 2015). "An array of EphB2 mutants were used to evaluate the role of receptor forward and reverse signaling on tumor formation: 1) EphB2(K662R)—kinase domain inactivated and inhibited in forward signaling but retaining ephrin-mediated reverse signaling." (PMID 25801123, 2015). "The localisation of ERBB3, EPHB2 and KI-67 within tumours was investigated using co-immunofluorescence." (PMID 26367378, 2015). "The expression levels of LGR5, EPHB2, CD44s and CD44v6 were increased at least 2-fold in 70.8% (34/48), 72.0% (36/50), 66.0% (33/50) and 86.0% (43/50) of tumour tissues compared to matched normal tissues." (PMID 26367378, 2015). "Our previous study showed that the overexpression of EphB2 suppressed tumor growth by inhibiting the cell cycle process and inducing cell apoptosis in CFPAC-1 cells." (PMID 24959213, 2014).
tumor (continued). "Summary of immunofluorescence staining analysis of EphB4 and EphB2 expression in normal and tumor urothelium specimens." (PMID 25148033, 2014). "Previously, a high expression of EphB2 was found to indicate advantageous tumor growth suppression with QYHJ treatment in CFPAC-1 cells." (PMID 24959213, 2014). "CFPAC-1, CFPAC-1 control RNAi and CFPAC-1 EphB2 RNAi cells with different levels of EphB2 expression were injected subcutaneously into female BALB/c nude mice to establish a tumor-bearing mouse model." (PMID 24959213, 2014). "It has previously been confirmed that EphB2 is a prognostic factor for several types of cancer and acts preferentially as a tumor suppressor in various cancers." (PMID 24959213, 2014). "For example, relapse samples gained mutations in transmembrance receptor tyrosine kinase genes EPHB2 and EPHB6, whose family member EPHA7 encodes a known soluble tumor suppressor for FL." (PMID 25123191, 2014). "The switch from EphB2 to EphB4 from normal bladder to tumor remains a prominent finding based on two orthogonal methods." (PMID 25148033, 2014). "A subcutaneously transplanted tumor model using cancer cells with different levels of EphB2 expression were established in vivo and received a four-week QYHJ intervention." (PMID 24959213, 2014). "The discrepancy in Western blot compared to immunofluorescence analysis suggests that Western blot is more sensitive than immunofluorescence or some tumor tissues used for Western blot were contaminated by normal cells thus giving a low level EphB2 signal." (PMID 25148033, 2014). "Previous studies on EPHB2 function were mainly focused on its role in tumor growth and brain development." (PMID 24551454, 2014). "Numerous studies have demonstrated that EphB2 preferentially acts as a tumor suppressor in various cancers, including colorectal (CRC), gastric and prostate cancer, which is unlike other RTKs that are generally regarded as oncogenes." (PMID 24959213, 2014). "In the current study, the different effects on tumor growth inhibition following QYHJ treatment in cells with different levels of EphB2 expression were investigated to reveal the mechanism." (PMID 24959213, 2014). "In this study, we found that EphB2, A2 and A3 were detected in both tumor and peritumoral liver tissues." (PMID 22860012, 2012). "For example, EphB2 activity is believed to have a function in suppressing tumour progression and metastasis." (PMID 18797457, 2008). "A role for EPHB2, a member of the Eph receptor tyrosine kinase family, as a tumor suppressor gene in colorectal carcinogenesis has been suggested by several recent findings." (PMID 18682749, 2008). "Ephrin A5 preferentially interacts with EphA2, A3, A5, A6, A7 and B2, of which only EphA2 and EphB2 were expressed to any significant degree in the tested normal or tumor samples." (PMID 16737551, 2006). "However, EphB2 expression has been reported to be dynamically regulated in different tumor progressions in multiple ways." (PMID 41551156, 2025). "EphB2 has been shown to promote tumor cell migration and invasion through forward signaling." (PMID 40943224, 2025). "In addition, EPHB2 promotes the proliferation, migration and invasion of tumor cells, inhibits tumor cell apoptosis, and leads to the activation of the PI3K/AKT/MAPK signaling pathway." (PMID 41322437, 2025). "In this study, we engineered Eb2Mab-12 into a mouse IgG2a-type (Eb2Mab-12-mG2a) and a human IgG1-type (Eb2Mab-12-hG1) mAbs, and evaluated antibody-dependent cellular cytotoxicity (ADCC), complement-dependent cytotoxicity (CDC), and antitumor efficacy in EphB2-positive tumor xenograft models." (PMID 40943224, 2025). "Studies on the expression and function of EPHB2 in various tumors have demonstrated its dual role in tumorigenesis and progression, acting as both a tumor suppressor and an oncogene, depending on the tumor type and microenvironment." (PMID 41322437, 2025).
tumor (continued). "Besides expression on tumor cells, EPHB2 can also be detected in monocytes, T cells, B cells, and some other immune cells." (PMID 41551156, 2025). "Importantly, reduced mRNA expression of LGR5, OLFM4, ASCL2 and EPHB2 was also observed in HG primary tumours in the TCGA dataset." (PMID 40473896, 2025). "By understanding the molecular mechanisms through which EPHB2 contributes to tumor aggressiveness and poor outcomes, we can develop targeted therapeutic strategies that may improve the prognosis and management of EC." (PMID 41322437, 2025). "Additionally, CTShigh TAMs secrete EPHB2, which contributes crucially to tumor-cell stemness via engagement to its receptor EFNB1." (PMID 38460015, 2024). "This suggests that negative regulation of EphB2 signaling in CRC may be a direct pathogenetic mechanism that leading to loss of tissue architecture and conferring tumor advantages in invasion and metastasis." (PMID 38651144, 2024). "In GC, EphB2 overexpression has been reported in tumor and serum samples." (PMID 39839790, 2024). "Potential therapeutic strategies for this tumor may involve targeting EphB2 expression and inhibiting its downstream signaling proteins." (PMID 39839790, 2024). "Functional experiments demonstrated that EPHB2 may increase tumour stemness and induce sorafenib resistance through the EPHB2/β-catenin/TCF1 positive feedback loop." (PMID 39144662, 2024). "EPHB2 promotes angiogenesis in tumor cells by introducing STAT3 phosphate into the nucleus." (PMID 36376513, 2023). "In addition, azurin can interfere with the autophosphorylation of tyrosine residues in the EphB2 kinase domain, thereby preventing tumor progression and inhibiting tumor growth." (PMID 37892918, 2023). "The hypoxic microenvironment possibly allows tumor cells to compete with immune cells for glutamine, and the significant activation of glutamine metabolism in tumor cells and the upregulation of EPHB2 expression make LUAD invasive and immunosuppressive." (PMID 37091977, 2023). "Furthermore, the expression levels of PIWIL4 were significantly higher in cancer than in adjacent mucosa, while EPHB2 expression was higher in adjacent normal tissues than in tumorous tissues." (PMID 37958942, 2023). "On the other hand, EphB2 was expressed at higher levels in tumours of patients with a lower BMI." (PMID 35949596, 2022). "Moreover, EphB2 expression is related to elevated metastatic potential, poor prognosis, and decreased survival of tumor patients." (PMID 35223830, 2022). "Moreover, EphB2 was downregulated in tumours from KKAy mice and obese patients (IRS, 6.58 with BMI <25 vs. 3.83 with BMI ≥25; P<0.001)." (PMID 35949596, 2022). "As the tumor grade increased, the expression rates of EphB2 lowered significantly." (PMID 35223830, 2022). "Finally, we put forward our viewpoint on the future prospects of cancer research focusing on EphB2, especially with regard to the effects of EphB2 on tumor immunity." (PMID 35223830, 2022). "This further implies that EphB2 also serves as a tumor suppressor in GC." (PMID 35223830, 2022). "In conclusion, it can be speculated that EphB2 might be involved in tumor immunity and this issue certainly worthy further investigation in future research." (PMID 35223830, 2022). "Moreover, inactivation of EphB2 has been demonstrated to facilitate tumorigenesis caused by APC mutations in the colorectum of APCMin/+ mice, indicating that EphB2 acts as a tumor suppressor in the large intestine." (PMID 35223830, 2022). "EphB2 is also a robust marker of intestinal tumor-initiating cells." (PMID 34831152, 2021). "Our previous work shows that, like other tumor suppressors, EphB2 has pro-apoptotic functions." (PMID 34360867, 2021). "EPHB2 is a tumor suppressor that affects the progression of CRC by acting on autophagy." (PMID 33937013, 2021).